ADAM12 (ADAM metallopeptidase domain 12)
Diseases named in the same sentence as ADAM12 in open-access papers (continued):
Sharing a sentence is not in itself a finding about the gene and the disease.
tumor (continued). "By contrast, depletion of ADAM12+ cells in the initial stages of tumorigenesis did not inhibit tumor growth, arguing against an initial feeder role for stromal cells." (PMID 37798557, 2023). "In addition, we for the first time, demonstrate that ADAM12 can further induce EMT and promote tumor progression in ccRCC through the EGFR/ERK signaling pathway." (PMID 36717944, 2023). "Consistent with a role for ADAM12+ cells in tumor hypoxia and acidosis, tumors lacking these cells showed decreased hypoxia and increased extracellular pH." (PMID 37798557, 2023). "In four publicly available gene expression datasets for CRC and non-cancerous colon tissue, high expression of ADAM12 was found in tumor tissue." (PMID 35413826, 2022). "The correlation between serum levels of ADAM12 and tumor tissue gene expression were not assessed, as no gene expression data are available for the CAIRO2 cohort." (PMID 35413826, 2022). "Possible effects of the overexpression of ADAM12 are the upregulation of growth pathways through enhanced expression of a subset of EGFR ligands and increased IGF-1R signaling, which contribute to increased tumor proliferation and metastasis." (PMID 35413826, 2022). "The advantage of measuring ADAM12 levels in blood samples rather than tumor biopsies is the non-invasive nature of the measurement." (PMID 35413826, 2022). "Indeed, both iRP-D26 and iRP-D28A showed upregulation of several genes known to facilitate human EVT and/or tumor cell invasion, including SDC2, TIMP3, MMP14, and ADAM12." (PMID 34154587, 2021). "In paraffin tissue sections, immunostaining of ADAM12 protein was predominantly identified in the cytoplasm of cancer cells and was not detectable in the tumor stroma." (PMID 33923541, 2021). "Since the interactions of several metalloproteins (integrin, ADAM12) with polysialic acid and the HNK-1 epitope play a crucial role in tumor tissues selected staining methods are proper tools to obtain essential information about the impact of the metal ions under study." (PMID 34869589, 2021). "Additionally, ADAM12 methylation was also tested in formalin-fixed, paraffin-embedded (FFPE (FFPE) tumours from these TNBC patients." (PMID 32019179, 2020). "Although the sample size was very small (n = 3), these data raise the possibility that ADAM12 is hypomethylated, relative to that of healthy women, not only in the tumour tissue, but also in the cfDNA released into the plasma from TNBC patients." (PMID 32019179, 2020). "A high TAK1 signature very clearly separated high-ADAM12 from low-ADAM12 tumors both in lung and colon, and the TAK1 activation score was positively correlated with ADAM12 expression, and negatively correlated with KAT2A expression, in both tumor types." (PMID 30753595, 2019). "Our previous analysis of two clinical datasets showed that elevated expression of ADAM12 mRNA is predictive of resistance to neoadjuvant chemotherapy in ER-negative breast cancer, independent of age, tumor size, grade, and the lymph node status." (PMID 28148288, 2017). "Among these, the metalloproteinase ADAM12 is highly expressed in human GBM and might play a role in the prominent proliferation of tumor cells through shedding of heparin-binding epidermal growth factor (HB-EGF)." (PMID 26437223, 2015). "Furthermore, the correlation observed between ADAM-12 and VEGF transcripts is of great interest since angiogenesis is an essential step of tumour progression." (PMID 16495931, 2006). "Additionally, ADAM12 vaccination did not promote tumor metastasis but induced vascular normalization, alleviated tumor hypoxia, and delayed PDAC growth." (PMID 39478152, 2024). "Here, we provide evidence that, in addition to already known factors such as PDGF and LOX, ADAM12 and rsBSG modulate the extracellular matrix as evidenced by the increased deposits of type 5 collagen in the stroma around the MCF7 tumor, producing increased ADAM12 in a nude mice tumor model system." (PMID 38892056, 2024).
tumor (continued). "Therefore, it seems that the tumor progressive role of ADAM12 is mediated through influencing apoptosis and not tumor cell proliferation." (PMID 38317965, 2024). "We found that mouse tumor tissue without Dox (expressing ADAM12) exhibited fibrillary collagen type 5 deposits, whereas no collagen type 5 was found in tumor tissue from mice which had received Dox in the drinking water and thus did not express ADAM12." (PMID 38892056, 2024). "A study focused on uncovering clinically significant aberrantly methylated genes in tumor cells reported three genes to be exclusively hypomethylated in TNBC, specifically Von Willebrand factor C and Epidermal Growth Factor domain-containing protein (VWCE), tetraspanin-9 (TSPAN9), and ADAM12." (PMID 38473804, 2024). "Interestingly, expression of ADAM12 in the primary tumor did not correlate with disease-free survival in the surgery alone group." (PMID 37495855, 2023). "Interestingly, we did not see any correlation of ADAM12 expression to tumor progression in rectal patients that only underwent surgical removal of the tumor, despite previous reports in some types of cancer." (PMID 37495855, 2023). "By interacting with a disintegrin and metalloproteinase 12 (ADAM12), transforming growth factor-β ligands (activin, myostatin and growth differentiation factor (GDF) 11), FSTL3 can either activate or inhibit these molecules in human non-tumor pathophysiologies and cancers." (PMID 36325361, 2022). "Therefore, we investigated whether ADAM12 may serve as a novel biomarker and/or therapeutic target in CRC, using human CRC cell lines, human CRC tissues, and an in vivo xenograft tumor model." (PMID 33923541, 2021). "However, the correlation between ADAM12 expression and B cells was not significant, suggesting that the tumor was heterogeneous in the antigens presented to cells recruited to the TME." (PMID 34604068, 2021). "All FFPE TNBC tumours showed 0% ADAM12 methylation, as their matched cfDNA (data not shown)." (PMID 32019179, 2020). "Nevertheless, our results are only correlative regarding the relationship between ADAM-12 and VEGF isoforms expression and further studies are needed to confirm our results and to precisely dissect the potential mechanisms linking ADAM proteases and tumour angiogenesis." (PMID 16495931, 2006). "In sharp contrast, ADAM-12 was strongly expressed in two cell lines, BZR and BZR-T33, derived from BEAS-2B cells by infection with recombinant retrovirus Zip-neo-v-Ha-ras or derived from a tumour formed by BZR cells injected subcutaneously into nude mouse, respectively." (PMID 16495931, 2006). "The diverse physiologic functions that ADAMs carry out, such as promoting cell multiplication and cleaving cytokines, chemokines, or their receptors, explain their contribution to cancer progression, regardless of whether ADAM12 levels are elevated in normal or tumor tissue." (PMID 39596804, 2024). "However, only ADAM12 is overexpressed in benign non-LCM tumor samples." (PMID 38317965, 2024). "Coculture of human stellate cells with primary tumor cells led to a significant upregulation of soluble ADAM12 that could be blocked by the TGF-β pathway inhibitor A83-01, confirming that active TGF-β ligand is present in these cocultures and able to drive ADAM12 secretion in stromal cells." (PMID 30442938, 2018). "However, there have been no reports on whether the expression of ADAM-12 is increased when tumor invasion and metastasis are enhanced." (PMID 24465799, 2014). "In agreement with previous reports, we observed that expression levels of ADAM9, ADAM10, ADAM12 and ADAM17 were increased in tumor versus adjacent non tumor tissues except for ADAM10 that was non-significant, all were associated with poor prognosis." (PMID 33805340, 2021). "We observed that TSPAN9 and ADAM12, but not VWCE, protein levels were significantly higher in tumours than in non-neoplastic tissues (p < 0.05)." (PMID 32019179, 2020).
tumor (continued). "We confirmed that TNBC tumours had significantly lower methylation levels than non-neoplastic samples in all analysed CpGs in VWCE, TSPAN9 and ADAM12 (p < 0.05)." (PMID 32019179, 2020). "Since we found DNA to be hypomethylated in tumour and adjacent-to-tumour tissue relative to non-neoplastic samples, leading to protein overexpression and worse OS in TNBC, our results suggested a potential key role for ADAM12 in TNBC, which prompted us to investigate its biological function in TNBC." (PMID 32019179, 2020). "In addition, investigation of ADAM12(S&L) and ADAM17 levels in laser-capture micro dissected (LCM) samples of BC showed that all of the three genes mentioned are upregulated in benign and malignant LCM tumor and malignant non-LCM samples." (PMID 38317965, 2024).
cancer (100 papers, 2006 to 2025). A tumor composed of atypical neoplastic, often pleomorphic cells that invade other tissues. "Another study was also designed to investigate this mutation given its possible correlation with cancer and to define the di-leucine motif's role in ADAM12 trafficking." (PMID 38317965, 2024). "Splice variants have been reported for ADAM9 and ADAM12 giving rise to secreted forms with implication in cancer cell invasion." (PMID 33805340, 2021). "ADAM12 is highly expressed in cancer of gastric and is implicated in the malignant growth of GC cells." (PMID 35178071, 2021). "An exception to this rule is the developmental gene ADAM12, highly expressed in the placenta, which encodes a metalloprotease re-expressed in cancers of diverse origins, such as breast, lung, liver, and colon malignancies." (PMID 30753595, 2019). "In line with the shed BSG ectodomain being a potential biomarker in cancer, we found a number of cancer-associated mutations in the region harboring the ADAM12 cleavage site." (PMID 31013576, 2019). "In this study we investigated the functional association of ADAM12 with TGF-β-dependent EMT in cancer." (PMID 26407179, 2015). "Overexpression of ADAM12 is implicated in the onset and progression of a number of disease conditions, including cancer." (PMID 26437223, 2015). "The present study was motivated both by the potential relevance of this documented mutation to cancer, as well as for determining the role of the di-leucine motif in ADAM12 trafficking." (PMID 22662180, 2012). "Similarly, miR-135b-5p has been linked to the regulation of MET and ADAM12, affecting invasion and proliferation in multiple cancers including PDAC." (PMID 40728965, 2025). "Loss of ADAM12 in cancer cells has been found to enhance the chemotaxis of B cells in vitro." (PMID 38317965, 2024). "In ADAM12 three somatic mutations that are cancer-associated were recognized." (PMID 38317965, 2024). "Interestingly, loss of cancer cell-derived ADAM12 expression increased the number of CD31+FAP− cells in murine tumors." (PMID 37495855, 2023). "Importantly, assessment of publicly available data revealed a number of cancer-associated BSG mutations in the ADAM12 cleavage region and when tested experimentally, we found that some of the mutations alter the susceptibility to ADAM12-mediated cleavage." (PMID 31013576, 2019). "More recently, the increased ADAM12 expression in cancer has been associated with EMT." (PMID 29765546, 2018). "Taken together, ADAM12 acts as an oncogene that is associated with poor prognosis in many cancers." (PMID 27557513, 2016). "ADAM12 has been reported to be associated with development and progression of many cancers." (PMID 27557513, 2016). "The increased expression of the Disintegrin and Metalloprotease ADAM12 has been associated with human cancers, however its role remain unclear." (PMID 26407179, 2015). "However, the association of ADAM12 methylation with CLL can be supported by the fact that CLL progression is slower than other cancers, suggesting methylation of ADAM12 may contribute to the speed of disease progression." (PMID 33507683, 2021). "Accordingly, concepts to treat cancer with inhibitors of BSG sheddases like TMPRSS11B or ADAM12 should be considered with caution, since highly malignant reverse Warburg cells would be supported by such treatments." (PMID 40508207, 2025). "Specifically, ADAM8 and ADAM12 consistently exhibited a significant upregulation trend in most cancer types." (PMID 39346916, 2024). "Given that soluble basigin is increased in the circulation of patients with a poor cancer prognosis, we explored the putative role of the ADAM12-generated basigin ectodomain in cancer progression." (PMID 38892056, 2024).
cancer (continued). "Cell-surface proteases, such as ADAM12, VNN1, and FLRT2, would cleave ECM components with the aid of SLIT2, CYR61, and ADAM12 in response to mechanical stimuli, allowing for cancer cells to migrate more easily." (PMID 39596804, 2024). "ADAM12 has been shown to be upregulated in many cancers and correlate with poor survival and chemoresistance, thus making it a potential candidate responsible for radioresistance." (PMID 37495855, 2023). "We and others have shown that ADAM12 is upregulated in multiple types of cancer and that its expression correlates with worse patient survival." (PMID 37495855, 2023). "In human cancer, ADAM12 stratifies patients with high levels of hypoxia and innate resistance mechanisms, as well as factors associated with a poor prognosis and drug resistance such as AXL." (PMID 37798557, 2023). "In this study, we investigated the potential role of ADAM12 in response of cancer to ionizing radiation." (PMID 37495855, 2023). "To further analyze if the expression of ADAM12 affects the colony forming capacity and survival upon radiation of cancer cells, we overexpressed catalytically active wildtype ADAM12 (A12) in MC38 cells." (PMID 37495855, 2023). "ADAM12, a member of the disintegrin-containing metalloprotease family, has been reported to be involved in a variety of diseases, including cancer (Nyren-Erickson, 2013 #32)." (PMID 36675796, 2023). "Analysis of populations of cells sorted from cancer tissue revealed the Fibroblast Activation Protein (FAP)-positive CAF population to be the predominant source of ADAM12 expression." (PMID 35413826, 2022). "The results indicated that the expression of ADAM12 in normal tissues was significantly lower than that in cancer tissues (p = 5.7e−05)." (PMID 35459884, 2022). "The results showed that the expression level of the ADAM12 protein in the cancer tissues was significantly higher than that in the adjacent tissues (p < 0.05)." (PMID 35459884, 2022). "Alternatively, spliced variants of ADAM12 and ADAM9 were identified in activated hepatic stellate cells and among those of ADAM9, the short form (ADAM9-S) promoted cancer cell invasion." (PMID 33805340, 2021). "Previously, upregulation of ADAM12 was shown to promote proliferation and inhibit apoptosis of various human cancer cells." (PMID 33923541, 2021). "ADAM12 seems to be a highly interesting research topic not only in terms of epigenetic changes but also with regard to the role of ADAM12 in the pathogenesis and progression of cancer and in the relationship between immune cell infiltration." (PMID 34604068, 2021). "The membrane type-I matrix metalloproteinase (MT1-MMP) also promotes cancer cell migration and invasion via EphA2 receptor cleavage ADAM12 modulates intracellular signaling by cleaving various membrane bound signaling receptors and their ligands." (PMID 33946495, 2021). "For example, binding of the 5th SH3 domain of Tks5 to the metalloproteinase ADAM12 acts in conjunction with Src to increase the shedding of growth factors at invadopodia during hypoxia-induced cancer cell invasion." (PMID 31999741, 2020). "HER ligands can also be released by ADAMs (ADAM10 and ADAM12) to promote cancer cell growth, migration, and invasion." (PMID 32637415, 2020). "ADAM-12 is induced during the EMT transition, a feature associated with claudin-low breast tumors, which are enriched in cancer stem cell (CSC) markers." (PMID 32466129, 2020). "In conclusion, the present study provides mechanistic insight on the pro-tumorigenic role of ADAM12 in cancer." (PMID 31013576, 2019). "Based on our findings, the soluble BSG fragment generated by ADAM12 can increase gelatinase activity when added to cancer cells in vitro." (PMID 31013576, 2019). "In conclusion, we identified ADAM12 as a novel basigin sheddase with a potential implication in cancer." (PMID 31013576, 2019).